CD4 (CD4 molecule)
Diseases named in the same sentence as CD4 in open-access papers (continued):
Sharing a sentence is not in itself a finding about the gene and the disease.
cryptococcosis (continued). "Histoplasmosis and cryptococcosis are two of the fungal diseases with higher prevalence in immunocompromised patients, especially in those with advanced HIV infection and CD4 T lymphocyte cell (CD4) counts lower than 150 and 100 cells/mm3, respectively." (PMID 30591013, 2018). "Serum cryptococcal antigen screening has an important role for the early diagnosis and treatment of cryptococcal infection in HIV-infected patients with low CD4 cell counts, particularly in patients with CD4 cellcount of <100 cells/mm3." (PMID 29214004, 2017). "In short, our study suggests that the value of CD4+/CD8+ ratios, CD8+ T-cell counts, or CD3+ T-cell counts is relatively limited in determining the immune status of patients with cryptococcosis." (PMID 28035481, 2017). "Here, we report that early TNF-α signaling is responsible for the acquisition of a DC1 phenotype by LALN DC, which optimally activates and polarizes CD4+ T cells to the Th17 and Th1 lineage in the LALN during the afferent phase of cryptococcal infection." (PMID 27406560, 2016). "This is recapitulated in animal models of cryptococcosis, where either immunodeficient transgenic mice or mice that are depleted of CD4+ and/or CD8+ T cells succumb to cryptococcal infection more rapidly than immunocompetent mice." (PMID 27165801, 2016). "However, the underlying immunological mechanisms that predispose HIV+ patients to cryptococcosis might not solely be attributable to CD4 depletion." (PMID 26252005, 2015). "In cryptococcosis, VEGF is secreted by a variety of leukocytes but especially by CD4+ T cells during antigen-specific responses to cryptococcal mannoprotein being presented by MHC-II molecules." (PMID 21253011, 2010). "Protection against experimental cryptococcosis in the absence of CD4+ T cells has been described for other whole organism cryptococcal vaccines." (PMID 38980038, 2024). "The CrAg screening of newly diagnosed HIV-infection- and HIV-positive people who are attending a hospital irrespective of their CD4 T cell count and viral load can minimize the number of missed cryptococcal infection cases in resource-limited settings." (PMID 37623607, 2023). "The CrAg screening of HIV-infected patients attending an emergency department can minimize the number of missed cryptococcosis cases irrespective of the CD4 T cell count and viral load." (PMID 37623607, 2023). "Cryptococcus can also appear in association with idiopathic CD4+ T-cell cytopenia without HIV infection, and the chance of disseminated cryptococcosis is high in patients with a CD4+ T-cell count lower than 400 cells/μl." (PMID 37251371, 2023). "For cryptococcosis, in the absence of vaccination, the development of an adaptive CD4+ T cell response is critical for host defenses against natural and experimental infections." (PMID 36732332, 2023). "All patients enrolled were intended to be screened for cryptococcosis, histoplasmosis, non-tuberculous mycobacterial infection and tuberculosis, regardless of the CD4 count." (PMID 36547618, 2022). "Eventually, a diagnosis of disseminated cryptococcosis was established and immunophenotyping revealed complete absence of circulating B and CD4+-T lymphocytes, and a markedly diminished CD8+-T lymphocyte count." (PMID 32624488, 2020). "Disseminated cryptococcal infection, manifesting as meningoencephalitis, usually occurs in individuals with depressed cell-mediated immunity, typically presenting as an opportunistic infection in advanced HIV (CD4 T-cell count <100/μL)." (PMID 33269293, 2020). "The other big problem is the absence of CD4 T-cell testing services in the country, and so screening for cryptococcal infection among HIV advanced patients is not performed." (PMID 31771096, 2019). "The second was a prospective study conducted in Buenos Aires, Argentina among HIV-infected persons with CD4 ≤ 100 cells/μL, without prior cryptococcosis and without antifungal therapy in the last 14 days." (PMID 29376931, 2016).
cryptococcosis (continued). "The first retrospective study was conducted in Lima, Peru among 368 ART-naïve adults with CD4 of ≤ 100 cell/μL without a history of cryptococcosis." (PMID 29376931, 2016). "Interestingly, our patient was not lymphopenic, and her CD4 + count was within normal ranges, in contrast to most descriptions of cryptococcal infection in the setting of fingolimod therapy." (PMID 40548133, 2025). "Our study identified histoplasmosis in 10% and cryptococcosis in 4% of participants, paralleling findings from Trinidad and Tobago’s largest HIV treatment site, where these infections were identified in 6% and 3% of PLHIV with CD4 counts < 350 cells/mm3, respectively." (PMID 39452647, 2024). "Termed “unmasking” disease, the hypothesis is that ART-triggered recovery of CD4 cells and reactivation of the immune system may be detrimental in persons with cryptococcal infection without first treating with antifungal therapy." (PMID 36675867, 2022). "This study was carried out with 162 cryopreserved (-20°C) serum samples from asymptomatic HIV patients with CD4+ ≤120 cells/μL collected from July 2016 to May 2019 for a previous study during which none of the patients developed cryptococcosis." (PMID 34495257, 2021). "The CD19+ B cells represented a greater proportion of circulating lymphocytes in blood among HIV-infected subjects with low CD4+ T cells than among healthy controls (median, 12% in cryptococcosis, 27% in noncryptococcosis, and 4% in healthy controls; analysis of variance [ANOVA], P < 0.001)." (PMID 31871098, 2020). "Indeed, CD8+ T cells participated in protection in a cryptococcosis model in a manner independent of CD4+ T cells but dependent on IFN-γ." (PMID 30940711, 2019). "In a randomized controlled trial of HIV-positive Ugandan adults, primary prophylaxis with fluconazole 200 mg thrice weekly was safe and effective in preventing invasive cryptococcosis in patients with CD4+ counts ≤200 cells/μL and negative serum cryptococcal antigen." (PMID 29376903, 2015). "The median CD4 count was higher for M. tuberculosis infection (52, IQR = 18 – 110) and Kaposi's sarcoma (46.5, IQR = 23.5 – 227.5) than for Pneumocystis carinii pneumonia (16.5, IQR = 9 – 40), herpes simplex (25, IQR = 9 – 63) and extrapulmonary cryptococcosis (13, IQR = 6.5 – 39)." (PMID 15538953, 2004). "Notably, the most recent report showed that patients with cryptococcal infection but without definitive immunodeficiency retained the ability to produce CD4+ and CD8+ T cell responses against cryptococcal antigens, which mainly biased towards the Th1 type (high IFN-γ, low IL-4)." (PMID 41017910, 2025). "Interestingly, not all HIV patients with low CD4+ T cell counts develop cryptococcosis." (PMID 29668826, 2018). "Before 2011, diagnoses of disseminated cryptococcosis, Kaposi sarcoma and PCP were often not recorded; among adults with results captured at their first CD4 count <200 cells/mm3, the annual prevalences were typically <1%." (PMID 28719610, 2017). "The study was performed on a prospective cohort of 77 volunteers: 53 HIV-positive (CD4+ T cell <200) patients, 18 healthy individuals (negative controls), and 6 HIV-positive patients with active proven cryptococcosis (positive controls)." (PMID 28493865, 2017). "Interestingly, this study revealed that HIV patients with positive cryptococcal antigenemia have lower CD4+ T-cell levels and higher plasma HIV-1 viral loads, as compared to patients who were not positive for cryptococcosis." (PMID 32963654, 2020). "We performed a GWAS of Cryptococcus susceptibility in a discovery cohort of 524 age-, gender-, and CD4 count-matched South African HIV-infected patients: cases with disseminated cryptococcosis (defined as positive serum CRAG and/or CM, n = 243) and controls (n = 281) with no cryptococcosis." (PMID 33269293, 2020).
glioblastoma (168 papers, 2011 to 2026). The most malignant astrocytic tumor (WHO grade IV). "The result is reduction of glioblastoma growth, associated with extensive infiltration of CD4+ cells and activated CD8+ CTLs in the TME." (PMID 39399167, 2024). "After these corrections, two significant associations between glioblastoma and subset abundance remained: naive CD4+ T cells and mature NK cells." (PMID 38318180, 2024). "They discussed CNS‐associated macrophages, tumor‐associated microglia/macrophages in glioblastomas, and CD4(+) T‐cell." (PMID 36514189, 2023). "Using an unbiased antigen discovery approach to probe the specificity of a TIL CD4+ T cell clone, we show that it recognizes a broad spectrum of peptides from pathogenic bacteria, commensal gut microbiota and also glioblastoma-related tumour antigens." (PMID 37198490, 2023). "The correlation between c-Met and FasL expressing GSCs with frequencies of CD8+, CD4+, T reg TILs, and microglia confirms the association between GSCs in the immune suppressive phenotype of glioblastoma tumors." (PMID 36299858, 2022). "In this view, it is conceivable that the increased expression of GITR on CD4+ T cells is linked to increased frequencies of regulatory T cell subsets and underlines the immune dysregulation in glioblastoma patients." (PMID 36497232, 2022). "A low expression of CD4+TILs was associated more with IDH1wildtype glioblastomas (n = 26) compared with IDH1mutant glioblastomas (n = 9)." (PMID 35201470, 2021). "The expression of CD204-associated TAMs, CD4-associated TILs, and Iba1-associated microglia was examined in 45 glioblastoma patients who received different treatment modalities." (PMID 35201470, 2021). "The purpose of this study was to assess the expression of CD204+ M2-polarized TAMs in glioblastomas and their relationship with CD4+TILs, Iba+microglia, and IDH1 mutation." (PMID 35201470, 2021). "The presence of low numbers of CD8+TILs in the glioblastoma microenvironment is associated with a poor outcome because cytotoxic lymphocytes are unable to kill tumour cells while CD4+TILs are completely suppressed." (PMID 35201470, 2021). "Here, an increased density of total CD3+ T lymphocytes and/or CD4+ or CD8+ subsets in spatial patterns suggesting interaction with the tumor microenvironment was observed in eight of nine (89%) POLE-mutated primary glioblastomas or spinal metastases compared to POLE WT controls." (PMID 37990341, 2023). "As high proportions of both blood and glioblastoma-associated CD4+ T-cell subsets expressed CXCR4, the geometric mean fluorescence intensity (gMFI) was compared to determine whether CXCR4 abundance on T-cell subsets differed between glioblastoma and blood samples." (PMID 35464424, 2022). "Here we report that CD4+ T cells are required for durable tumor control in syngeneic murine models of glioblastoma multiforme after treatment with an oncolytic herpes simplex virus (oHSV) engineered to express IL-12." (PMID 39885128, 2025). "Here the authors report that CD4 + T cells are required for the therapeutic activity of an oHSV-engineered to express IL-12 in preclinical glioblastoma models." (PMID 39885128, 2025). "CIITA induces MHC class II expression in glioblastoma cells, endowing them with surrogate antigen-presenting capability that elicits robust CD4+ T cell-mediated adaptive anti-tumor immunity." (PMID 40861816, 2025). "Ferroptotic glioblastoma cells significantly increased T cell infiltration, with a pronounced effect on CD4+ T cells." (PMID 41300529, 2025). "Again, both CD8+ and CD4+ PTPRZ1-TCR-T cells were activated by the primary glioblastoma cell line D170_44." (PMID 39893177, 2025). "Among effector T cell populations, CD4+ helper T cells are also present within the glioblastoma microenvironment, though they remain less extensively characterized than their CD8+ counterparts." (PMID 40867165, 2025).
glioblastoma (continued). "Another study also found a significant difference in the percentage of TIM-3 positivity of peripheral CD4+ T cells in glioblastoma patients compared to healthy controls." (PMID 40072074, 2025). "While ferroptotic glioblastoma cells attracted CD4+ T lymphocytes by releasing ATP, their activation was inhibited because of extracellular ATP." (PMID 41300529, 2025). "This study by Goods and colleagues also showed that the percentage of TIM-3 positivity on infiltrating CD4+ T cells was significantly higher than that on peripheral CD4+ T cells in glioblastoma patients." (PMID 40072074, 2025). "Whilst both CD8+ and CD4 + T cells assist in glioblastoma tumour clearance, myeloid cells protect glioblastoma tumour cells from ZIKV infection through the secretion of type 1 interferons." (PMID 41166287, 2025). "The cell exhaustion marker TIGIT was more abundant on lymphocytes of glioblastoma patients in comparison to HC and RRMS patients, on CD4+ lymphocytes of glioblastoma patients compared to HC, and on NK cells of glioblastoma in relation to RRMS patients." (PMID 39497174, 2024). "What is more, activated CD4+ TSCM (Tc-I 32) and naïve CD4+ Tc (Tc-I 12 & Tc-I 22) were elevated in the PB of RRMS compared to glioblastoma patients." (PMID 39497174, 2024). "Tumor-infiltrating lymphocytes (TILs) serve as representative markers for the predominant presence of CD8+ cytotoxic T lymphocytes (CTLs), CD3+ T cells, and CD4+/FoxP3+ regulatory T cells (Tregs) within the glioblastoma (GBM) tumor microenvironment (TME)." (PMID 38732975, 2024). "Another study recently reported that the IFNγ from CD4+ T cells in the solid tumor microenvironment drives microglial phagocytosis of glioblastoma cells." (PMID 38893085, 2024). "Glioblastoma patients had significantly fewer naive CD4+ T cells, but higher percentages of mature NK cells than controls." (PMID 38318180, 2024). "Collectively, these data reveal that glioblastoma-mediated CD4+ and CD8+ T cell and NK cell suppression is due, at least in part, to dysregulated TIM-3 and BAT3 expression and the associated downstream immunoregulatory and dysfunctional effects." (PMID 39513882, 2024). "Khan and colleagues investigated the efficacy of PD‐1 ICB, a CD40 agonist, and a combination of both in a CT2A glioblastoma mouse model that contained dysfunctional CD4+ T cells and was unresponsive to anti‐PD‐1 ICB." (PMID 39169517, 2024). "Meanwhile, we examined changes in the quantities of CD45+CD103+ DCs, CD3+CD8+ T, and CD3+CD4+ T cells in glioblastoma microenviroment." (PMID 39192971, 2024). "AT-0174 exhibited an ideal profile for adjunct treatment of glioblastomas with the first-line chemotherapeutic drug temozolomide to prevent development of CD4+ Treg-mediated chemoresistance." (PMID 39048947, 2024). "Dexamethasone treated patients with glioblastoma, metastases or meningioma have significantly less naive CD4+ T cells and alternative monocytes compared to epilepsy and healthy controls." (PMID 38318180, 2024). "In another study, dexamethasone treatment before glioblastoma resection affected the main immune cell populations, including CD4+ and CD8+ T cells, CD66b+ neutrophils, CD14+ monocytes, non-Vδ2 γδT cells, and NK cells (especially CD56high)." (PMID 38390330, 2024). "We FACS-purified CD8+ and CD4+ conventional T cells from d12 PDG-Ink4a glioblastoma, a timepoint where T cell infiltration is at its peak, and performed RNA sequencing (RNA-seq)." (PMID 37081259, 2023). "A recent study demonstrated very broad specificity of a MHC Class II-restricted CD4 TCR isolated form TILs of a glioblastoma patient." (PMID 37965314, 2023). "As the circulating Treg content is unchanged and Tregs proliferate within the tumor, we propose that both local expansion and CD4+ conventional T cell conversion act in concert to increase Treg content in RT + Conc.IT-treated glioblastoma." (PMID 37081259, 2023).
glioblastoma (continued). "Compared with the glioblastoma core, the invasive margins have reduced microglial activation and motility, CD4+ T and NK cells, and have increased homeostatic microglia." (PMID 37324244, 2023). "(ii) Resveratrol combined with radiotherapy decreases percentage of CD3+CD8+T and IFN-γ+CD8+T cells and increases percentage of (CD4+CD25+Foxp3)/CD4+T cells in glioblastoma tumor tissues." (PMID 36276282, 2022). "There was also a significant decrease in the proportion of CD8+ Temra cells in glioblastoma compared to blood samples, while the proportions of CD4+ Temra cells in blood and glioblastoma were negligible." (PMID 35464424, 2022). "In this illustrative case, the tumor-specific CD4+ T-cell numbers and phenotype behaved as treatment efficacy biomarkers, highlighting the key role of the latter in glioblastoma immunotherapy." (PMID 35628206, 2022). "Like CD4+ glioblastoma T cells, CXCR3 was expressed moderately by all CD8+ T-cell subsets, and there was a significantly greater proportion of CXCR3+CD8+ Tem cells in glioblastoma biopsies compared to paired blood samples." (PMID 35464424, 2022). "Conversely, CD4+ CD25high “Tregs” demonstrate only a modest proportional increase within GBM compared to the PBMCs of glioblastoma patients." (PMID 35163235, 2022). "Autopsy brain tumor specimens showed viable glioblastoma cells on hematoxylin and eosin staining, and persistent intratumoral infiltration of CD4+ and CD8+ T lymphocytes that first became apparent in the early post-dose period." (PMID 35864115, 2022). "In contrast, the stem bark ethanol and DMSO extracts of A. coriaria harvested in central Uganda had high cytotoxicity against the human glioblastoma cell line (U87.CD4.CXCR4) with CC50 of 6.4 and <4 μg/mL, respectively." (PMID 35103066, 2022). "Two phase I trials of adult glioblastoma patients have already demonstrated that personalized neo-antigen vaccines can elicit neoantigen-specific CD4+ and CD8+ T cell responses." (PMID 35464481, 2022). "There was a significant decrease in the abundance of CD49d on the CD4+ Tem population in glioblastoma compared to blood samples, and a significant increase in CD49d gMFI on CD4+ Tregs in glioblastoma." (PMID 35464424, 2022). "In our patient, monocytes and macrophages are the predominant immune cells in the glioblastoma component, while CD4+ lymphocytes and NK cells are found in the epithelioid component." (PMID 36703629, 2022). "In contrast, there was a significant enrichment of CD4+ and CD8+ Tcm, Tem, and Trm populations in glioblastoma biopsies, with CD4+ Tcm and CD8+ Tem and Trm populations most abundant overall." (PMID 35464424, 2022). "Intratumoral administration of G47∆ showed a survival benefit and safety in residual or recurrent glioblastoma patients with high CD4+ and CD8+ TILs infiltration." (PMID 36513720, 2022). "In contrast, CD49a (integrin α1) expression was significantly enriched within CD4+ Tcm, Tem, Temra and Tregs, and CD8+ Tcm, Tem and Temra subsets in glioblastoma infiltrates compared to blood, and both CD4+ and CD8+ Trm cells expressed this integrin." (PMID 35464424, 2022). "Strikingly, there was a significant increase in the abundance of CXCR4 on all CD4+ T-cell subsets in glioblastoma compared to blood samples." (PMID 35464424, 2022). "Previous studies have identified that memory T cells, including Tcm, Tem and Temra, and CD4+ Tregs can infiltrate glioblastoma." (PMID 35464424, 2022). "CXCR6, an established marker of CD69+CD103+ Trm cells, was expressed on CD4+ Trm cells as anticipated, but also enriched in all other CD4+ T-cell subsets in glioblastoma compared to blood." (PMID 35464424, 2022). "CD8+ and CD4+ T cells in IDH-wt glioblastoma had higher expression of cytotoxicity, interferon, and cellular stress pathways than IDH-mut gliomas." (PMID 35464481, 2022).